BCL6 (BCL6 transcription repressor)
Diseases named in the same sentence as BCL6 in open-access papers (continued):
Sharing a sentence is not in itself a finding about the gene and the disease.
tumor (continued). "Although in normal GC B-cells MUM1 and BCL6 are mutually exclusive, in tumor cells both proteins are coexpressed, and we observed a more significant influence of MUM1 for non-GCB group, in agreement with it post-germinal marker feature." (PMID 31185999, 2019). "According to this observation, in most DLBCL cell lines, effective tumor cell killing requires the concomitant inhibition of BCL6 and BCL2." (PMID 31336593, 2019). "Western blot was performed to investigate the effect of BCL6 on the malignant behavior of tumor cells in protein level." (PMID 30420967, 2018). "Abnormal expression of BCL-6 can directly regulate cell differentiation, proliferation and apoptosis to promote tumor growth and differentiation." (PMID 30666200, 2018). "The tumor was also positive for B-cell CLL/lymphoma 6 (Bcl6), CD10, and showed greater than 95% reactivity for Kiel 67 (Ki67)." (PMID 29415774, 2018). "Interphase FISH analysis showed red and green separate fluorescent spots in the same nuclei of tumor tissues indicating BCL6 translocation (1C arrow)." (PMID 29854311, 2018). "Tumor cells with BCL6 knockdown resulted in significant reduction of cell migration and invasion in Transwell assays." (PMID 30420967, 2018). "Endothelial activation by tumor cell supernatant resulted in peak levels of Bcl-6 and BCoR transcripts after 1–2 h and downregulation by 4 h." (PMID 27880939, 2017). "Accumulating evidence has demonstrated that the tumor suppressor functions of Smads are compromised by oncogene products, such as c-Ski, Bcl6, c-Myc, Evi-1 and STAT3, through direct Smad–oncoprotein interactions during carcinogenesis." (PMID 28455959, 2017). "A potentially adverse effect of Bcl-6 blockade in cancer therapy would be feasible considering the important role of angiogenesis in tumor expansion (or bone marrow angiogenesis in lymphoproliferative disease)." (PMID 27880939, 2017). "Several genomic regions were preferentially amplified or deleted in tumours harbouring IDC, including gain of BCL6 and loss of MTOR, along with gains of a region harbouring CDK2 and ERBB3." (PMID 28067867, 2017). "While the mouse retina model investigated physiological angiogenesis, a possibly promoting effect of Bcl-6 inhibition on pathological tumor vascularization was of particular concern." (PMID 27880939, 2017). "With a P-value threshold at 0.05, only 3 genes (BCL6, BCL2, and HIST1H2BM), containing the regulatory mutation blocks, show significant differential expression between the tumor and normal samples." (PMID 28765546, 2017). "Here, we found that Ikaros, a tumor suppressor encoded by IKZF1, directly binds to both the BCL6 and BACH2 promoters where it suppresses BCL6 and promotes BACH2 expression in B-cell ALL (B-ALL) cells." (PMID 28030830, 2017). "Knockdown of BCL6 also significantly increased the percentage of REH tumor cells in G0/G1 phases and reduced G2/M phases in line with the observed reduction of cell density in the time course assay." (PMID 27015556, 2016). "REH tumor cells with constitutive overexpression of BCL6 in the PD population showed a significant reduction in viability when compared to vector controls following exposure to chemotherapy." (PMID 27015556, 2016). "Immunohistochemistry (IHC) of MYC, BCL2 and BCL6 was performed on tumor samples from 114 patients with PCNS-DLBCL." (PMID 27286976, 2016). "In this study, the results suggest that targeting BCL6 is a major mechanism by which miR-10a exerts its tumor-suppressive and pro-apoptotic function in DLBCL cells." (PMID 27815824, 2016). "Consistent with the in vitro findings, in vivo chronic overexpression of BCL6 during Ara-C treatment resulted in a modest reduction in the tumor burden in femurs of mice when collected 24 hours following the conclusion of Ara-C treatment." (PMID 27015556, 2016).
tumor (continued). "Collectively, our findings provide a novel apoptotic regulatory pathway in which LITAF, as a transcription factor, inhibits the expression of BCL6, which leads to activation of the intrinsic mitochondrial pathway and tumor apoptosis." (PMID 27764808, 2016). "The expression of BCL-6 on tumor cells was significantly lower (mean percentage of BCL-6-positive cells 0 vs 34.0 % in EBV-positive DLBCL of the elderly vs other cases; P = 0.038)." (PMID 26084760, 2016). "Forced chronic expression of BCL6 during co-culture with BMSC or HOB sensitized the tumor to chemotherapy induced cell death." (PMID 27015556, 2016). "Utilizing ALL cell lines, and primary patient tumor cells we observed that tumor cell BCL6 protein abundance is decreased in the presence of primary human bone marrow stromal cells (BMSC) and osteoblasts (HOB)." (PMID 27015556, 2016). "Limited to the phenotyping of Tfh by the expression of Bcl-6, these results suggest that similarly to Th2, reduced tumor infiltration with Tfh cells correlates with disease aggressiveness and poor prognostic value." (PMID 27237631, 2016). "PD tumor cells were “rescued” from BCL6 overexpression by BCL6 chemical inhibition, as demonstrated by the increase in PD REH cell viability following 79-6 and chemotherapy exposure relative to the overexpression only cells." (PMID 27015556, 2016). "As many chemotherapy regimens require tumor cell proliferation for optimal efficacy, we investigated the consequences of constitutive BCL6 expression in leukemic cells during co-culture with BMSC or HOB." (PMID 27015556, 2016). "Since in Drosophila and human cells, Src upregulates Stat activity, tumours showing high Bcl6 and Src or Yes1 expression would be predicted to be sensitive to this combined therapeutic regime." (PMID 26187947, 2015). "We found in 2/3 PMBL cell lines that downregulation of BCL6 / STAT6 sensitizes the tumor cells for treatment with immuno-chemotherapeutic agents." (PMID 25594020, 2014). "We found that expression of BCL6 increased tumor cell viability, migration, invasion, and survival as well as expression of cyclinD1, and CXCR4 in vitro." (PMID 24917186, 2014). "Together, these observations suggest that miR-127 functions as a novel tumor suppressor that coordinates with oncogene BCL6 to contribute to the pathologies of aging and cancer." (PMID 24282530, 2013). "So far, many commonly expressed genes in tumor cells of both entities were identified, such as BCL6, CD75, EMA, J-chain and PU.1, as well as a typical kappa light chain restriction." (PMID 24244368, 2013). "BCL6 and pSTAT6 are oncogenic factors, and both have been shown to contribute to tumor cell viability." (PMID 23852366, 2013). "Of note, averages of BCL6+/pSTAT6− and BCL6−/pSTAT6+ fractions surmount to ~46% of the tumor cells in primary PMBL cases leaving ~54% CD19+ BCL6−/pSTAT6− cells." (PMID 23852366, 2013). "We quantitatively examined ten primary PMBL tumor samples by double IF for pSTAT6 and BCL6 and verified staining in tumor cells using the B-cell surface marker CD19 (left cutouts)." (PMID 23852366, 2013). "CD10 and BCL6 was positive not only at in the tumor follicles, but also at in the interfollicular and diffuse areas of some cases." (PMID 24047469, 2013). "The miR-127 also exhibits tumor suppressor activity by targeting BCL6 proto-oncogene and it is silenced in various cancer cell lines." (PMID 22848594, 2012). "Hsa-mir-127, reported to be methylated in neoplastic cells and inversely proportional to the expression of BCL6, plays as tumour suppressor." (PMID 22190944, 2012). "MiR-127 is silenced in cancer cells but normally expressed in fibroblasts, and it can suppress the expression of proto-oncogene BCL6, which endows miR-127 with the characteristic of a tumor suppressor." (PMID 23284895, 2012).
tumor (continued). "Patients with presence of BCL2, CCND2, BCL6 and LMO2 mRNA in plasma showed higher expression levels for each gene in tumor tissue, although we only observed a significant association for BCL2 mRNA." (PMID 20016842, 2009). "Immunohistochemistry analysis for BCL2 and BCL6 was performed on tumor tissue from 24 and 26 DLBCL patients, respectively, in our series." (PMID 20016842, 2009). "A possible effector of miR-127 was identified as the proto-oncogene BCL6, a key player in B-cell apoptosis and neoplasia." (PMID 18588681, 2008). "As BCL6 is a master regulator of the cell cycle, we considered the possibility that Fx1 may work to inhibit tumor expansion directly." (PMID 41145211, 2026). "In addition, the expression of proteins related to apoptosis, DNA damage repair, and BCL6 in different groups of tumor samples was detected via western blotting." (PMID 40821118, 2025). "Additionally, we observed that BCL6 enhanced HGSOC cell proliferation, invasion, and migration, whereas BCL6 knockout significantly reduced tumor growth in nude mice." (PMID 40777995, 2025). "The requirement of CD4+ T cells for recall response and the requirement of Bcl-6 expression in late-stage CD4+ T cells for prolonged survival prompted us to ask if M002 treatment had the potential to increase the memory feature of CD4+ T cells in the tumor." (PMID 39885128, 2025). "Our results suggested that IRF4 promotes BCL6 and thereby may contribute to tumor progression in ccRCC." (PMID 40607252, 2025). "As the deletion of Bcl6 in Treg cells resulted in significantly delayed tumor progression in the 4NQO-induced carcinogenesis model, we hypothesized that Bcl6 may represent a potential therapeutic target in HNSCC treatment." (PMID 40290124, 2025). "In addition, given the key role of BCL6 in tumor pressure tolerance, our study revealed that YK01 and TMZ had synergistic anti-GBM effects, and the combination of YK01 effectively inhibited the in situ tumor growth of GBM and significantly prolonged survival." (PMID 40821118, 2025). "Moreover, BCL6 was overexpressed in GBM tumor samples compared with adjacent tissues according to database analysis." (PMID 40821118, 2025). "Moreover, BCL6 overexpression was found to be positively correlated with advanced tumor stage and poor prognosis in patients with HGSOC." (PMID 40777995, 2025). "Moreover, Bcl6 inhibitor FX1 repressed the tumor progression of subcutaneous HNSCC and exhibited a synergized effect with PD-1/PDL-1 ICB." (PMID 40290124, 2025). "Importantly, Bcl6 inhibition repressed the tumor growth of murine HNSCC and exhibited synergistic effects with immune checkpoint blockade therapy." (PMID 40290124, 2025). "In addition, given the key role of BCL6 in tumor pressure resistance, our study has revealed that YK01 and TMZ have synergistic anti-GBM effects, which provides new strategies to improve GBM resistance." (PMID 40821118, 2025). "Precancerous clusters showed enrichment in tumor progression-related regulons, including transcription factors (TFs) linked to tumor proliferation and cell cycle progression (STAT1, BCL6, ETV5) and potential tumor suppressors (ELF5, LTF, RXRG, CEBPD), as well as EMT-related regulons." (PMID 39872221, 2025). "MCL-1 and BCL-6 gene expression showed significant associations with advanced stage and high tumor grade (P < 0.001), but not with menopausal status or hormone receptor status (P > 0.05)." (PMID 40612845, 2025). "Some researchers utilized imDC-Exo with low immunogenicity to deliver BCL6 siRNA to tumor tissues." (PMID 40142991, 2025). "However, recent reports identified that BCL6 acts as a pro‐tumor growth factor in various malignancies, playing a crucial role in promoting resistance to anti‐tumor drugs and chemotherapy." (PMID 40470696, 2025). "Above data only showed quantity of T cells infiltration increased in Bcl6 knockout tumor, but whether the infiltrated T cells are activated as indicated in single-cell RNA sequencing data was still not unclear." (PMID 38956432, 2024).
tumor (continued). "Importantly, there were four out of seven mice (about 57%) been tumor free for the BCL6 knockout in combination with anti-PD1 therapy." (PMID 38956432, 2024). "Whether T cells is the immune population regulated by Bcl6 to promote tumor progression and which subpopulation of T cells is accounted for HCC regression is not answered." (PMID 38956432, 2024). "Furthermore, we used survival curve to analyze the effect of Bcl6 on tumor progression in longer time period and found that knocking out of Bcl6 significantly extended mice survival time." (PMID 38956432, 2024). "Bcl6 knockout increased total immune cell infiltration, T cell infiltration, and T cell activation; we thus used flow cytometry to analyze the tumor immune cells infiltration." (PMID 38956432, 2024). "BCL6, a gene involved in B-cell differentiation, is frequently mutated or overexpressed in PCNSL and has been detected in both tumor tissue and CSF, but its clinical significance as a biomarker remains unclear." (PMID 39144147, 2024). "Notably, when we sacrificed the survived mice on day 120 post-surgery for BCL6 KO#1 and KO#2 groups, we found that all the remaining mice were tumor free." (PMID 38956432, 2024). "Then, we used in vivo imaging to monitor tumor growth, and found that Esm1 could partially rescue the phenotype of Bcl6 knockout." (PMID 38956432, 2024). "BCL6, in turn, inhibited the generation of tumour‐specific Tex‐term cells from Tpex cells." (PMID 39169517, 2024). "BCL6, identified as a master transcription factor for regulating follicular helper cell proliferation, has been demonstrated to inhibit apoptosis, thereby promoting tumor invasion, migration and growth." (PMID 38951817, 2024). "Indeed, from single cell RNA sequencing and flow cytometry data, we demonstrated that cancer cells with high expression of Bcl6 inhibit tumor immune cell infiltration, and suppress tumor-infiltrating CD4+T cells and CD8+T cells activity." (PMID 38956432, 2024). "The 3q gains within the BCL6 locus differed between the tumor cell line and the -U14 and U20 LCLs, indicating that the gains in tumor and LCLs originated independently; since this region is frequently affected in BL, this might be biologically significant." (PMID 38057307, 2023). "BCL6 is also essential for the stability of Tregs that promotes tumor growth." (PMID 36879282, 2023). "From a clinical perspective, low BCL6 expression was closely related to larger tumor size, later pN stage, and poor survival outcome, which might serve as a compelling candidate biomarker for predicting metastasis and prognosis in GC patients." (PMID 37060074, 2023). "Nonetheless, whether synergistic effects between EBV and MYC/BCL2/BCL6 aberrations contribute to the pathogenesis of this subset of tumours remains to be established." (PMID 36836878, 2023). "In conclusion, BCL6 expression and its tumor suppressor role in GC could be strengthened by RNF180/RhoC pathway." (PMID 37060074, 2023). "In summary, we describe the mechanism by which BCL6 played a tumor inhibitory role in GC." (PMID 37060074, 2023). "In summary, BCL6 should be considered a potential intermediate tumor suppressor to inhibit the malignant progression and induce ferroptosis, which might be a promising molecular biomarker for further mechanistic investigation of GC." (PMID 37060074, 2023). "Bcl-6, an essential marker of the germinal center activation pathway was not included in the protein panel, but will be important to further examine possible tumor induced B cell activation through the germinal center pathway." (PMID 36052068, 2022). "In addition, iRGD-Exo mediated BCL6 siRNA delivery markedly inhibited tumor growth in DLBCL in vivo." (PMID 35982974, 2022).
tumor (continued). "For instance, simultaneous inhibition of DNA methylation by 5-aza-dC and histone deacetylation by 4-phenylbutyryl acid in tumor cells upregulates miR-127 expression and downregulates the expression of proto-oncogene bcl6, thereby highlighting miR-127 as a tumor suppressor." (PMID 36483544, 2022). "Importantly, Bcl6+ macrophages stably maintained cell identity, gene signature, metabolic profile, and pro-tumor property even after long-term culture in tumor-free medium, which were hence termed stem cell-like memory macrophages (SMMs)." (PMID 36542153, 2022). "First, we investigated the effects of BCL6 knockdown on tumor cell growth in vitro." (PMID 36377663, 2022). "In addition, several lines of evidence have shown that the combination of BCL6 with other therapeutic agents leads to enhanced tumor regression." (PMID 36377663, 2022). "Since tumor adaptive resistance to genotoxic stress was attributed to BCL6 transactivation, we tested whether pharmacological inhibition of BCL6 could restore the sensitivity of resistant cancer cells to genotoxic agents." (PMID 35503721, 2022). "FISH assays for MYC/BCL2/BCL6 in tumor tissues were performed in 11 (65%) patients." (PMID 36483984, 2022). "Next, we assessed the anti-tumor ability of the iRGD-Exo-BCL6 siRNA1 in vivo." (PMID 35982974, 2022). "Furthermore, intravenously injected iRGD-Exo delivered BCL6 siRNA to tumor tissues, resulting in inhibition of tumor growth in DLBCL." (PMID 35982974, 2022). "The data thus indicated that Bcl6+ macrophages preferentially assumed mitochondria- metabolism and restrained glycolytic pathway, ensuring their metabolic fitness during competing with ever-growing tumor cells, a glycolysis-favoring population." (PMID 36542153, 2022). "This supports the hypothesis that TFs such as BCL6 likely play an important role in mediating the tumor microenvironment differences observed between AFR and 10.13039/501100001828EUR ancestry patients with CRC." (PMID 35711675, 2022). "Although Smc3/Bcl6 tumors showed higher variability in the total numbers of somatic mutations, these were not significantly different than tumor cells from the Bcl6 (Wilcoxon p=0.24)." (PMID 34621263, 2021). "Indeed further examination of chromatin compartment distribution in Smc3/Bcl6 vs Bcl6 and tumor cells showed very little difference between these genotypes." (PMID 34621263, 2021). "No somatic alterations in FBXO11, MSH6 or BCL6 were present, nor did we find hypermutation in the tumor or a mutational signature related to MMR deficiency." (PMID 33811277, 2021). "Thus, the stable of BCL6 stabilizes the levels of Tregs, and inhibits the anti-tumor immune response." (PMID 33468159, 2021). "However, it is important to note that while BCL6 inhibition did increase the response of paclitaxel, the effect was modest in the tumor study." (PMID 33932086, 2021). "Recently, the tumor suppressor function of BCOR has been confirmed in vivo in a Myc-driven lymphomagenesis model as well as in transgenic mice expressing a truncated form of BCOR (partial internal deletion) that cannot bind to BCL6." (PMID 33468080, 2021). "We hypothesize that the heterozygous germline FBXO11 deletion in the patient would result in retained BCL-6 expression in the tumor." (PMID 33811277, 2021). "Knockdown of BCL6 resulted in increased tumor regression in mice treated with paclitaxel." (PMID 33932086, 2021). "We hypothesize that the functional state and stability of tumor infiltrating Treg cells has been altered to a state in which Bcl6 is essentially required." (PMID 32477338, 2020). "Tumor-infiltrating CD62L+Bcl6+ cells possessed a high potential to proliferate." (PMID 32845913, 2020).